ANGPTL8 (angiopoietin like 8)
Diseases named in the same sentence as ANGPTL8 in open-access papers (continued):
Sharing a sentence is not in itself a finding about the gene and the disease.
hepatocellular carcinoma (15 papers, 2011 to 2024). A malignant tumor that arises from hepatocytes. "It is also referred to as lipasin, angiopoietin-like protein 8 (ANGPTL8), refeeding induced in fat and liver (RIFL), or hepatocellular carcinoma-associated gene TD26." (PMID 39030467, 2024). "Betatrophin is one of the names given to C19orf80, which is also called Hepatocellular Carcinoma-Associated Gene TD26, Refeeding Induced Fat and Liver (RIFL), Lipasin, and ANGPTL8." (PMID 27672665, 2016). "ANGPTL8 has also been given other names such as C19orf80, Hepatocellular Carcinoma-Associated Gene TD26 and RIFL (refeeding induced in fat and liver)." (PMID 26784326, 2016). "Recent studies found that the serum ANGPTL8/betatrophin concentrations were significantly higher in hepatocellular carcinoma patients than in healthy controls." (PMID 34646087, 2021). "Insulin also stimulated the promoter activity of Angptl8, including the consensus binding motif for Hnf-1, in hepatoma cell lines and mouse primary hepatocytes, thereby confirming that the mechanism of insulin stimulation involves Hnf-1 binding." (PMID 32561878, 2020). "In fact, the knockdown of both Hnf-1α and Hnf-1β decreased the expression of Angptl8 protein in both mouse hepatoma cells and mouse primary hepatocytes." (PMID 32561878, 2020). "We aimed to evaluate the effects of recombinant ANGPTL8 on Wnt/β-catenin signaling in human liver carcinoma cells (HepG2) and their viability." (PMID 31998458, 2019). "ANGPTL8 is a recently defined gene also called C19orf80, LOC55908, refeeding-induced fat and liver (RIFL), TD26, hepatocellular carcinoma-associated gene, lipasin, and betatrophin." (PMID 28754724, 2017). "ANGPTL8 may act as a moderate suppressor of hepatocellular carcinoma cell proliferation by affecting Wnt signaling modulators." (PMID 37294581, 2023). "Silencing Hnf-1 in hepatoma cells and mouse primary hepatocytes reduced Angptl8 protein levels." (PMID 32561878, 2020). "In addition, Angptl8-shock induces the rhythmic expression of clock genes in mouse Hepa1c1c-7 hepatoma cells." (PMID 31388006, 2019). "However, Angptl8 shock in mouse Hepa1c1c-7 hepatoma cells for 2 h induced the expression of key clock regulators, whereas Per1 induction was the most significant compared to other factors." (PMID 31388006, 2019). "In their opinion, ANGPTL8 may act as a moderate suppressor of human liver carcinoma cells." (PMID 38107478, 2023). "ANGPTL8/betatrophin may act as a moderate suppressor of hepatocellular carcinoma." (PMID 34646087, 2021). "So, ANGPTL8 may act as a mild suppressor against hepatocellular carcinoma cells." (PMID 31998458, 2019). "Overall, the present study revealed that ANGPTL8 affects mRNA expression of two key regulators of Wnt signaling pathway, β-catenin and WIF-1, and inhibits proliferation of the hepatocellular carcinoma cell line HepG2 moderately." (PMID 31998458, 2019). "Additionally, Angptl8 shock did not influence the mRNA and protein expression levels of PirB in mouse hepatoma cells." (PMID 31388006, 2019).
diabetic nephropathy (14 papers, 2018 to 2025). "ANGPTL4 and ANGPTL8, which regulate lipid metabolism and inflammatory responses, have been associated with both diabetic nephropathy and retinopathy." (PMID 40137149, 2025). "ROC curve analysis also emphasized the sensitivity and specificity of Ang2 alone and in combination with ANGPTL8 and Ang1 as diagnostic tools for diabetic nephropathy." (PMID 38790911, 2024). "On the other hand, the larger AUC for ANGPTL8 underscores its potential as a robust biomarker for diabetic nephropathy, offering promise for improved diagnostic precision and patient stratification in clinical practice." (PMID 38790911, 2024). "Previous studies found that ANGPTL8 levels were increased in diabetic nephropathy and associated with eGFR." (PMID 34167540, 2021). "A previous research studied the association of ANGPTL8 and diabetic nephropathy and found that ANGPTL8 was predictive of the progression of diabetic nephropathy." (PMID 30409151, 2018). "Therefore, the present study investigated the association between DN and circulating ANGPTL8 in people with T2D, compared to people with diabetic nephropathy." (PMID 37762544, 2023). "In addition, the study also showed that ANGPTL8 could increase the risk of diabetic nephropathy (DN) and might serve as a predictor for DN progression." (PMID 30021607, 2018). "In individuals with diabetic nephropathy, our data presents a notable rise in the levels of circulating Ang2, ANGPTL8, and ANGPTL4." (PMID 38790911, 2024). "ANGPTLs, particularly ANGPTL3, ANGPTL4, and ANGPTL8, play pivotal roles in regulating lipid metabolism and energy homeostasis, with emerging implications for diabetic nephropathy." (PMID 38790911, 2024). "In previous studies of diabetic nephropathy, serum ANGPTL8 was found to be positively correlated with patient BMI." (PMID 33853533, 2021). "Previous studies found that ANGPTL8 levels were increased in diabetic patients, especially in patients with diabetic nephropathy." (PMID 34557469, 2021). "It has been suggested that ANGPTL8 may be an advanced endocrine regulatory factor involved in the development of diabetic kidney disease, which suggests that ANGPTL8 is closely associated with renal disease." (PMID 38107478, 2023). "Logistic Regression Analysis of ANGPTL8 and resistin for diabetic nephropathy in all patients." (PMID 34603198, 2021). "Abnormal ANGPTL8 elevation may lead to dysregulated lipid metabolism in the kidney, which offers a possible explanation for the role of ANGPTL8 in the development of diabetic nephropathy." (PMID 30409151, 2018). "Interestingly, a study showed that there was a more significant increase in ANGPTL8 levels in patients with diabetic nephropathy compared to diabetic patients without the associated nephropathy." (PMID 40725697, 2025). "Furthermore, studies suggest that ANGPTL8 may be a biomarker for diabetic retinopathy and diabetic nephropathy, with evidence supporting its correlation with serum creatinine levels and glomerular filtration rate (GFR) decline." (PMID 40137149, 2025). "Whether or not the alteration in ANGPTL-8 and resistin level can be a predictive maker for increased diabetic nephropathy risk remains unclear." (PMID 34603198, 2021). "Logistic regression analysis of ANGPTL8 and resistin respectively for diabetic nephropathy in the non-NAFLD and NAFLD population." (PMID 34603198, 2021). "Furthermore, other studies demonstrated that circulating ANGPTL8 levels were much higher in patients with diabetic nephropathy than in diabetic patients without RD." (PMID 34557469, 2021). "The Ang2 levels increased in conjunction with higher levels of ANGPTL8 and ANGPTL4 and the ACR but showed a negative relationship with the eGFR and systolic blood pressure, suggesting possible involvement in diabetic nephropathy." (PMID 38790911, 2024).
diabetic nephropathy (continued). "Interestingly, the present study found that the association between ANGPTL8 levels and CKD existed not only in diabetic patients but also in non-diabetic individuals, indicating that ANGPTL8 may play a role in kidney disease, not just high glucose-mediated damage in diabetic nephropathy." (PMID 34557469, 2021).
non-alcoholic fatty liver disease (14 papers, 2017 to 2025). "A study showed that ANGPTL8 is linked to lipid metabolism involving glucocorticoids, a cause of non-alcoholic fatty liver disease in chronic exposure, and they demonstrated that ANGPTL8 levels and expression were suppressed with glucocorticoids through glucocorticoid receptors." (PMID 40725697, 2025). "Studies showed that ANGPTL8 was positively correlated with the incidence of non-alcoholic fatty liver disease (NAFLD) and significantly elevated in mice and humans with NAFLD." (PMID 29719529, 2018). "Circulating ANGPTL8 concentrations are elevated in patients with non-alcoholic fatty liver disease and liver steatosis." (PMID 30021605, 2018). "Circulating ANGPTL8 is increased in patients with T2D or non-alcoholic fatty liver diseases, which makes ANGPTL8 an attractive therapeutic target for metabolic syndromes." (PMID 29255244, 2017). "Angiopoietin-like 8 (ANGPTL8) is a liver- and adipose tissue-produced protein that predicts non-alcoholic fatty liver disease (NAFLD) and altered metabolic homeostasis in the general population as well as in persons with common and genetic obesity, including the Prader–Willi syndrome (PWS)." (PMID 33067796, 2021). "Additionally, Angptl8 participates in the pathogenesis of metabolic disorders, such as non-alcoholic fatty liver disease and diabetes." (PMID 31388006, 2019). "Besides, ANGPTL8 also participated in some other disorders such as non-alcoholic fatty liver disease and renal dysfunction." (PMID 29719529, 2018).
coronary artery disease (10 papers, 2018 to 2025). "More studies are assessing whether there is potential for ANGPTL8 as a marker to measure long-term risk of secondary coronary events from stabilized coronary disease build-up." (PMID 40725697, 2025). "Similarly, a protein truncation variant (PTV) of ANGPTL8 has been shown to reduce the incidence of coronary artery disease (CAD) in a Finnish population, while another study has shown a significant reduction in cardiovascular events in CAD patients with high ANGPTL8 levels." (PMID 34582711, 2021). "Recently, studies revealed that serum ANGPTL8 levels were significantly elevated in patients with coronary artery disease (CAD), thoracic aortic dissection (TAD) or essential hypertension." (PMID 35851270, 2022). "Notably, studies have revealed elevated serum ANGPTL8 levels in coronary heart disease patients relative to their healthy counterparts, and a positive correlation was observed between ANGPTL8 levels and disease severity." (PMID 38107478, 2023). "In summary, I here propose a hypothesis that ANGPTL8 inhibition can simultaneously reduce TG and increase HDL-C plasma levels, with the potential to reduce the risk of coronary artery disease." (PMID 34869703, 2021). "However, according to the FinnGen study, in carriers of the T allele of the ANGPTL8 SNP (rs760351239), the odds of coronary artery disease were 47% lower than in non-carriers." (PMID 34869703, 2021). "Besides, whether ANGPTL8 concentration is altered in the patients with coronary artery disease (CAD) is still unclear." (PMID 30021607, 2018). "However, whether ANGPTL8 concentration is altered in the patients with coronary artery disease (CAD) has not been reported." (PMID 30021607, 2018).
Hyperglycemia (10 papers, 2016 to 2025). An increased concentration of glucose in the blood. "Our study investigated the potential associations between ANGPTL8 gene variants (rs737337 and rs2278426) and certain metabolic parameters, such as hypercholesterolemia, hyperglycemia, ALT, and AST levels." (PMID 37679750, 2023). "Another study of an Arab cohort suggested that the gene variants rs737337 (T/C) and rs2278426 (C/T) are associated with lower risk of hypercholesterolemia and hyperglycemia supporting the role of ANGPTL8 in lipid and glucose metabolism." (PMID 37947641, 2023). "A study of an Arab cohort found that the study variant and another variant, rs737337 from ANGPTL8, are associated with a lower risk of hypercholesterolemia and hyperglycemia." (PMID 37755252, 2023). "In our study, diabetic patients had higher ANGPTL8 levels, accompanied by increased incident rates of metabolic disorders, such as hyperlipidaemia, hyperglycaemia and hypertension, consistent with findings from previous observational studies." (PMID 32746907, 2020). "While ANGPTL8 did not reverse hyperglycemia in overtly hyperglycemic NOD mice or alter glucose homeostasis of non-diabetic NOD mice, ANGPTL8 reduced blood glucose levels in 12LOKO NOD mice." (PMID 31741751, 2016).
Hypertension (10 papers, 2018 to 2023). The presence of chronic increased pressure in the systemic arterial system. "This association with hypertension may be explained by a strong correlation of ANGPTL8 with high sensitive C-reactive protein (HsCRP) found in some studies." (PMID 32317770, 2020). "They demonstrated that ANGPTL8 regulates hypertension and that arterial remodelling involves accelerated constriction, proliferation, and migration of VSMCs through the promotion of PI3K-AkT pathway activation." (PMID 38107478, 2023). "Herein, our clinical data demonstrated that ANGPTL8 levels were elevated in patients with hypertension complicated with myocardial hypertrophy and negatively associated with the thickness of the ventricular wall." (PMID 35851270, 2022). "In control subjects, ANGPTL8 levels were also associated with waist-hip ratio (WHR), systolic blood pressure (SBP), HbA1c and incidence of hypertension (all p values < 0.05)." (PMID 32746907, 2020). "ANGPTL8 was shown to be an independent biomarker for hypertension, and the incidence of hypertension in TAD patients is very high." (PMID 32034642, 2020). "Multiple logistic regression analysis adjusted showed that subjects in the highest tertile of ANGPTL8 were more likely to have hypertension OR = 3.8, 95% CI = (1.5-9.8), p-Value = 0.005." (PMID 29490644, 2018). "In conclusion, ANGPTL4 and ANGPTL8 levels are increased in both plasma and adipose tissues of subjects with hypertension." (PMID 29490644, 2018). "The elevated levels of ANGPTL4 and ANGPTL8 in hypertensive subjects highlight their potential involvement, their potential role as biomarkers for hypertension and their therapeutic value in hypertension given their roles in regulating lipid metabolism." (PMID 29490644, 2018). "In conclusion, our data illustrate that ANGPTL4 and ANGPTL8 levels in both plasma and adipose tissues are increased in subjects with hypertension." (PMID 29490644, 2018). "The gene expression of ANGPTL4 and ANGPTL8 in adipose tissues displayed a similar pattern as the circulating levels in that their expression was elevated in subjects with hypertension." (PMID 29490644, 2018). "Moreover, serum ANGPTL8 levels were increased in patients with hypertension and atherosclerotic cardiovascular disease." (PMID 35851270, 2022). "Moreover, serum ANGPTL8 levels were negatively correlated with LAEDd and LVEDd in patients with hypertension and MH." (PMID 35851270, 2022). "The association between ANGPTL8 levels and kidney function decline showed increased significance in individuals with BMI ≥ 24 kg/m2, older age (≥ 60 years), hypertension and no CVD (all p value < 0.05)." (PMID 34167540, 2021). "Further, ANGPTL8 plasma levels are increased in hypertension patients." (PMID 32034642, 2020). "Serum ANGPTL4 and ANGPTL8 levels are increased in patients with hypertension." (PMID 29940978, 2018). "Given the role of ANGPTL3, ANGPTL4 and ANGPTL8 in regulating lipid metabolism we hypothesised that their levels might be increased in subjects with hypertension." (PMID 29490644, 2018). "Additionally, people with highest tertiles of ANGPTL8 had higher odds of having hypertension (odd ratio [OR] = 3.8, 95% confidence interval [CI] = (1.5-9.8), p-Value = 0.005." (PMID 29490644, 2018). "We later demonstrated increased circulating levels of ANGPTL8 and ANGPTL4 in adults with hypertension." (PMID 38189043, 2023). "Conversely, ANGPTL4 and ANGPTL8 levels were elevated by 1.6- and 3-fold, respectively, in subjects with hypertension compared to those in subjects without hypertension (both p < 0.05)." (PMID 29490644, 2018). "The circulating levels of ANGPTL4 and ANGPTL8 were increased in subjects with hypertension compared to those in subjects without hypertension in both the entire study population and the T2D subgroup." (PMID 29490644, 2018).
Hypertension (continued). "Dyslipidaemia is a risk factor for hypertension development; however, the roles of ANGPTL3, ANGPTL4 and ANGPTL8 in subjects with hypertension have not yet been established." (PMID 29490644, 2018). "In this study, we measured the expression of ANGPTL3, ANGPTL4 and ANGPTL8 in both plasma and adipose tissue in subjects with and without hypertension." (PMID 29490644, 2018). "This study compared the plasma and adipose tissue levels of ANGPTL3, ANGPTL4 and ANGPTL8 in age- and body mass index-matched subjects with and without hypertension." (PMID 29490644, 2018). "However, estimates of the association between ANGPTL8 and kidney function decline in individuals with CVD or without hypertension were not statistically significant." (PMID 34167540, 2021). "However, ANGPTL8 levels were not significantly different in TAD subjects according to the presence or absence of hypertension (584.95 ± 30.49 pg/mL vs. 548.45 ± 28.05 pg/mL, respectively; P = 0.40)." (PMID 32034642, 2020). "Similarly, ANGPTL4 and ANGPTL8 levels were also elevated in subjects with T2D and hypertension than in those with T2D but not hypertension." (PMID 29490644, 2018). "Therefore, we examined the plasma and adipose tissue levels of ANGPTL3, ANGPTL4 and ANGPTL8 in subjects with or without hypertension using ELISA and real-time PCR." (PMID 29490644, 2018). "Serum ANGPTL8 was increased in subjects with hypertension and myocardial hypertrophy (MH) compared with healthy people (2108 ± 134.86 vs 1218 ± 156.74 ng/ml) but was lower than that in subjects with hypertension without complications (2108 ± 134.68 vs 2516 ± 289.21 ng/ml)." (PMID 35851270, 2022). "Similarly, in subjects with T2D, ANGPTL4 and ANGPTL8 levels (p < 0.05), but not ANGPTL3 levels, were significantly higher in subjects with hypertension." (PMID 29490644, 2018).
gestational diabetes (9 papers, 2015 to 2025). Carbohydrate intolerance first diagnosed during pregnancy. "The expression of ANGPTL3, ANGPTL4, and ANGPTL8 in the placenta of women with gestational diabetes has previously been shown to be positively correlated with birth weight of the offspring." (PMID 39984579, 2025). "Compared to healthy controls, subjects with gestational diabetes mellitus present increased ANGPTL8 in maternal and cord blood." (PMID 29719529, 2018). "The aim of the study was to compare maternal serum, cord blood serum, and placental angiopoietin-like 8 (ANGPTL8) levels in the third trimester of pregnancy in women with and without gestational diabetes and explore the potential underlying mechanism." (PMID 35529083, 2022). "In addition, the increase of ANGPTL8 was also found in prediabetes and gestational diabetes mellitus (GDM)." (PMID 34582711, 2021). "Recent work has identified a reduction in brown adipose tissue (BAT) in mothers with gestational diabetes, with reduction in concentrations of BAT-derived adipokines, neuregulin-4 and angiopoietin-like protein 8 (ANGPTL8)." (PMID 37442824, 2023).
hyperlipidemia (8 papers, 2020 to 2025). "The elevated levels of ANGPTL8 were correlated with risk factors related to mortality, such as sex, age, BMI, smoking, eGFR, creatinine, and hyperlipidaemia." (PMID 32746907, 2020). "Primary nephrotic syndrome showed links between ANGPTL8 and the development of hyperlipidemia and proteinuria." (PMID 40725697, 2025). "This study aimed to investigate the expression characteristics of ANGPTL8 in patients with primary nephrotic syndrome and its possible correlation with hyperlipidemia and proteinuria." (PMID 33853533, 2021). "ANGPTL3, ANGPTL4, and ANGPTL8 are important factors in the regulation of the metabolism of lipids and lipoproteins, providing new hope for the treatment of hyperlipidemia." (PMID 32440963, 2020). "ANGPTL8 levels were associated with BMI high-density lipoprotein (HDL) and incidence of hyperlipidaemia in the diabetic patients (all p values < 0.05)." (PMID 32746907, 2020). "Our data also suggest that ANGPTL8 functions in PNS hyperlipidemia." (PMID 33853533, 2021). "Furthermore, subgroup analyses indicated that the relationship between ANGPTL8 levels and RD was significant in females, individuals aged > 60, individuals with a BMI < 24, individuals without DM, individuals with DM, and individuals without hyperlipidaemia." (PMID 34557469, 2021).